MMP9 (matrix metallopeptidase 9)
Diseases named in the same sentence as MMP9 in open-access papers (continued):
Sharing a sentence is not in itself a finding about the gene and the disease.
cancer (continued). "It has been shown that matrix metalloproteinase MMP9 can effectively degrade the main components of extracellular matrix and play an important role in the process of cancer cell abscission, invasion and metastasis." (PMID 35812753, 2022). "In fact, glucose depletion was found to induce matrix metalloproteinases MMP-2 and MMP-9, suggesting that the increase in cellular proline concentration in cancer cells is a result of collagen degradation." (PMID 35733940, 2022). "To better understand the potential mechanism of MMP-9 expression in cancers, we analyzed its expression in ACC, KIRC, and DLBC using GSEA." (PMID 35178444, 2022). "By putting all these findings into perspective, it is believed that the E3Ab decreases migration in cancer cells by interfering with the role of MMP-9 in the context of migration." (PMID 35204811, 2022). "The stroma fibroblasts and MSC can also produce MMPs, in particular, MMP-1, MMP-2 and MMP-9 in cell culture, when incubated with the conditioned medium or directly with cancer cells." (PMID 35163805, 2022). "Some targets, including EGFR, PDGFR, FAK, CXCR4, and MMP9, have corresponding inhibitors that have been approved or are under active clinical trials for cancer treatment." (PMID 35919862, 2022). "Transwell assay results showed that EIF5B silencing decreased the migration of HCC cells by suppressing EMT and decreasing the expression levels of MMP-2 and MMP-9, which are required for cancer progression." (PMID 37305324, 2022). "CEACMA6 is known to exert a pro-invasive role in several carcinomas via regulation of matrix metalloprotease-9 (MMP9), which is also hypomethylated." (PMID 36291828, 2022). "The use of ketogenic diet, in combination with other conventional cancer therapy, is expected to provide a noticeable reduction in the expression of MMP-9 in different types of cancer." (PMID 34287243, 2021). "Emerging evidence suggests that SFN downregulate MMP-1, MMP-2, MMP-7, and MMP-9 and therefore intervenes in cancer cells invasion and angiogenesis." (PMID 34552922, 2021). "Fibronectin coding genes were found to be up-regulated in studies describing cancer cell migration and various EMT markers such as vimentin, E-cadherin, MMP2 and MMP9, which were all associated with and used to measure cellular invasion." (PMID 33809554, 2021). "E-cadherin being one of these critical receptors that induces MMP-9 in cancer cells is a real possibility." (PMID 34198494, 2021). "In the early stages of metastasis, neutrophils release MMP-9 to promote angiogenesis, playing an important role again by not only facilitating cancer growth but also providing more routes for cancer cells to escape." (PMID 34674757, 2021). "The cancer cell corresponds to its histologic grade produce the MMP-9, MMPs divide and degrade all the structural elements of the extracellular matrix (ECM) so that MMP plays a significant role in both lymphogen and haematogenous metastases." (PMID 33850625, 2021). "Among matrix metalloproteinases (MMPs), MMP-9/2 are key enzymes involved in the proteolysis of extracellular matrices in the inflammatory process and in cancer." (PMID 34885656, 2021). "As two of the most widely studied matrix metalloproteinases (MMP), MMP-2 and MMP-9 play important roles in developmental biology and act as cancer biomarkers." (PMID 34654351, 2021). "In fact, serum levels of MMP-9 are not only indicative of the prognosis of patients with PC but are also directly involved in cancer progression." (PMID 34299570, 2021). "Cancer cells in suspension were trapped by immobilized antibodies in the hydrogel and the activity of MMP9 secreted from the trapped cells was monitored by following the cleavage of the FRET-linked peptides." (PMID 33477883, 2021). "Amongst involved proteases, MMP-9 and MMP-2 are profoundly implicated in cancer invasion and metastasis as they are the most essential for the degradation of base membranes." (PMID 34068885, 2021).
cancer (continued). "Among them, MMP-2 and MMP-9 are remarkably up-regulated in malignant tumors and contribute to cancer invasion." (PMID 33718164, 2021). "In HCC, MMP-2 and MMP-9 are two main components of MMPs that play an important in cancer cell invasion and migration." (PMID 34066056, 2021). "Increased expression of MMP-9 induced by galectin-7, which occurs at both the mRNA and protein levels, has in many cases been documented by adding recombinant human galectin-7 to cancer cells." (PMID 34198494, 2021). "We therefore suggest that CCA-1.1 can be used to suppress cancer cell migration, which is mediated by the repression of the MMP-9 activity." (PMID 34181339, 2021). "The addition of benign cell lysate resulted in a significant increase of MMP9, VEGFA, ApoE, ANG, and MMP10, and the addition of cancer cell lysate resulted in a significant increase of MMP9, CA9, PAI1, ApoE, A1AT, ANG, and MMP10." (PMID 34204951, 2021). "We focused on proteins determining angiogenic properties (vascular endothelial growth factor, VEGF-A), migratory phenotype (vimentin, Vim) and invasive/metastatic potential (Matrix metalloproteinases, MMP-2 and MMP-9) of cancer cells." (PMID 33670389, 2021). "We examined the effects of FQs on MMP-9 production in cancer cells following transforming growth factor beta (TGF-β) and phorbol 12-myristate 13-acetate (PMA) stimulation." (PMID 34769032, 2021). "MMP-9 induction was less prominent in ETS1-3A-overexpressing cancer as compared with that observed when ETS1 was overexpressed." (PMID 34023818, 2021). "This in vitro study with neuroglioma cells demonstrated that inhalational anesthetics exerted the anti-cancer effects via the miR-138/HIF-1α, miR-210/HIF-1α and miR-335/MMP9 pathways in this specific cancer cell line." (PMID 33919449, 2021). "The transcriptional activation of β-catenin downstream targets, including MMP-9, Myc, Axin2, and cyclin D1, is able to promote cell cycle progression, cell proliferation, and metastasis in the progression of cancer." (PMID 34545072, 2021). "Based on its broad functions, several studies and meta-analyses have identified MMP9 as a potential biomarker in various cancers." (PMID 33573134, 2021). "In turn, TSP-2 expression was negatively correlated with T stage, metastasis, grade, cancer cell proliferation and MMP-9 expression." (PMID 33923108, 2021). "C5AR2 overexpression also upregulated the expression levels of MMP2 and MMP9, which were reported as oncogenes correlated with metastasis and invasion in various cancers." (PMID 34595119, 2021). "STAT3 activation plays an important role in metastasis, and STAT3 increases the expressions of MMP2 and MMP9, which act as key mediators of the metastatic process of cancer cells." (PMID 34876128, 2021). "In contrast, upregulation of MMP-9 in breast cancer and other cancers enhances tumor cell migration and invasion." (PMID 34067095, 2021). "The majority of MMPs and TIMPs were mainly expressed in cancer cells at the invasive front (MMP-9: 97.3% of the tumors, MMP-11: 98.7%, MMP-14: 94.0%, TIMP-1: 86.7%, TIMP-2: 96.7%)." (PMID 33669393, 2021). "Gelatinases (MMP-2 and MMP-9) play essential roles in cancer progression and metastasis, as they can break down basal membranes." (PMID 35068948, 2021). "MMPs are also involved in several inflammatory pathologies including cancer, where in particular MMP-9 favor angiogenesis, cell migration, and metastasis." (PMID 35723387, 2021). "Several studies indicated that matrix metalloproteinases (MMPs) such as MMP-2, MMP-7 and MMP-9 play important roles in the migration of ECs and even angiogenesis of various cancers by degrading extracellular matrix (ECM) and releasing various growth factors." (PMID 33573006, 2021). "In accord with this observation, NET-induced activation of the same pathway, requiring NE and MMP9 activity, awakes slow-cycling cancer cells." (PMID 34503307, 2021).
cancer (continued). "Especially, MMP2 and MMP9 are of particular interest for their role in the development and progression of early cancer." (PMID 34006286, 2021). "MMP9 expression indices in HCC tissues were lower than those in para-cancer tissues (t value = 138.600, p < 0.0001)." (PMID 34376644, 2021). "Regarding the importance of MMP-9 as a biomarker, the 82 kDa isoform has already been considered in several forms of cancer, while the 65 kDa isoform has escaped the attention of researchers for the reasons given in this work." (PMID 35723387, 2021). "More than 50 MMP inhibitors have been investigated in various cancers, but all have failed, and in a study consisting of 37 HNSCC patients treated with cisplatin and cetuximab, a high mRNA expression of MMP9 was associated with objective treatment response." (PMID 34283070, 2021). "In particular, granule proteins such as neutrophil elastase (NE) and matrix metalloproteinase 9 (MMP9) released with NETs have been shown to awaken dormant cancer cells by remodeling the ECM and inducing cancer cell proliferation in mouse models." (PMID 34567000, 2021). "EMT is also associated with the increased expression and activities of MMP-2 and MMP-9, which can stimulate the metastasis of cancer cells." (PMID 33912463, 2021). "Particularly MMP-2 and MMP-9 are important factors of basal membrane degradation and the matter of interest in cancer research." (PMID 34684168, 2021). "FN1 was previously shown to be able to activate MMP2 and MMP9 expression during malignant tumor progression, facilitating cell migration, invasion, and distant metastasis." (PMID 34758823, 2021). "MMP-2 and MMP-9 are found in OvCa patient ascites and aid cancer cell invasion through type IV collagen degradation." (PMID 33810259, 2021). "In the anti-oncogenic subnetwork, the down-regulated MMP-9 targeted by up-regulated miR-451a were enriched in Pathways in cancer." (PMID 33630973, 2021). "As an anticancer candidate, apigenin inhibits cancer cells proliferation by downregulating AKT phosphorylation as well as metastasis by downregulating MMP-9 expression." (PMID 34830091, 2021). "This was performed through a western blot analysis assay to examine the expression of MMP-2 and MMP-9 in cancer cells after treatment with different nano-formulations." (PMID 34950642, 2021). "In particular, NET-derived DNA acted as a proteolysis scaffold by releasing elastase and MMP9, promoting cancer cell proliferation through bioactive epitopes in cleaved laminin." (PMID 34116679, 2021). "The extracellular matrix and the basal lamina can be degrade and broken up by MMP-9, thereby the cancer cells will finish invasion and remote metastasis." (PMID 34249706, 2021). "Some granule proteins (MMP-9 and ARG-1) released by activated neutrophils are associated with cancer progression." (PMID 34674757, 2021). "Thirdly, we traced cancer patient prospectively after surgery, which clarify the temporality of prognostic ability of MMP-9 for OSCC." (PMID 33735248, 2021). "Mechanistic analysis revealed that this process was potentially via NE/MMP-9-induced cleavage of laminin, which subsequently led to the activation of integrin α3β1 signaling in dormant cancer cells." (PMID 34476216, 2021). "Cathepsin K is able to cleave and activate pro-MMP-9 and is involved in inflammation and in some types of cancer." (PMID 35723387, 2021). "MMP2 and MMP9 in particular among the MMPs are considered to be highly valuable enzymes due to the important role they play in disease pathogenesis such as cancer and Alzheimer’s disease." (PMID 34209215, 2021). "In summary, our studies show that B. burgdorferi is able to invade breast epithelial cells and its infection can increase the migration and invasion of cancer cells as well as increase the expression of MMP9." (PMID 34827233, 2021). "Several studies have investigated MMP9 as a target molecule for the diagnosis and treatment of inflammatory conditions and cancer." (PMID 34577904, 2021).
cancer (continued). "According to reports, RECK can reduce the invasion and migration of malignant tumors by abating MMP-9 secretion." (PMID 34790697, 2021). "Investigators studied the signatures of MMP9 in healthy and cancer breast tissue with various molecular subtypes which showed a marked increase in the expression of MMP9 in cancer tissues relative to ordinary ones." (PMID 34221232, 2021). "Among these pathways, STAT3 is crucial for activating the MMP9 gene and cancer stem phenotype in the 3D tumoroid model." (PMID 33562088, 2021). "The levels of NET-associated proteases, including neutrophil elastase (NE) and matrix metalloproteinase 9 (MMP9), are increased in cancer." (PMID 34116679, 2021). "PM-induced oxidative stress has been accepted as a key molecular mechanism of many inflammatory modulators, such as tumor necrosis factor-α (TNF-α), interleukins IL-1, IL-6, IL-8, and COX-2, including MMP-9 expression and cancer cell metastasis." (PMID 34439757, 2021). "MMP-9 plays a number of important physiological functions but is also responsible for many pathological processes, including cancer invasion, metastasis, and angiogenesis." (PMID 34183752, 2021). "This article shows that interleukin‐33‐stimulated macrophages produce MMP‐9 that eliminates cell surface molecules in immune cells and cancer cells." (PMID 34486239, 2021). "MMP2 and MMP9 are recognized as two major enzymes in the degradation of type IV collagen and correlate with an invasive phenotype of cancer cells (Vihinen and Kähäri, 2002)." (PMID 34988077, 2021). "Functionally, SH3PXD2B can recruit membrane type-1 matrix metalloproteinase (MT1-MMP) to the incomplete podosomes to activate MMP2 and MMP9, leading to matrix degradation and cancer cell invasion." (PMID 33906640, 2021). "To confirm the role of GSK3β in promoting MMP-9 expression, we examined its induction in cancer cells co-transfected with the ETS1 expression vector and GSK3β siRNA." (PMID 34023818, 2021). "For example, cancer cells were less capable of colonizing the lung of MMP-9-deficient mice than the lung of wild-type mice, and MMP-9 null mice develop fewer cancers than wild-type mice." (PMID 34439874, 2021). "Overexpression of GPNMB by retrovirus transfection in glioma cells is accompanied by MMP-3 and MMP-9 increase, both increasing metastasis and cancer invasion." (PMID 34054862, 2021). "A pan-cancer survival analysis revealed that the downregulation of MMP9, Runx2 and Snail by CM had a significant impact on survival outcomes (p < 0.00001)." (PMID 34373756, 2021). "MSLN expression has been linked to matrix metallopeptidase 9 (MMP-9) expression at the invading edges of tumors, illustrating its role in promoting cancer invasion." (PMID 34439085, 2021). "EMT biomarkers such as Vimentin, N-cadherin, and MMP9 are overexpressed in cancer and are involved in promoting cancer cells metastasis." (PMID 34458309, 2021). "A nutrient mixture containing AA also inhibited secretion of MMP-9 monomer and dimer in a broad set of cancer cell lines, and similar MMP inhibitory activity has been observed in other human and animal models." (PMID 34445461, 2021). "The ability of galectin-7 to augment MMP-9 expression in cancer cells has also been established using cancer cells transfected with eukaryotic expression vectors containing the gene encoding galectin-7 (i.e., LGALS7)." (PMID 34198494, 2021). "Some target genes, such as MMP9 and cyclin D1, are involved in oncogenesis, regulating cancer proliferation and metastasis." (PMID 33407510, 2021). "5-MTP suppresses cancer cell COX-2 and MMP-9 expression and inhibits cancer cell migration and invasion." (PMID 34771474, 2021). "Although MMP-9 is strongly regarded as a promising target for cancer treatment, MMP-9 inhibitors have thus far failed in clinical trials due to serious side effects and no therapeutic benefit." (PMID 34769032, 2021). "The protein expression of MMP-2 and MMP-9 in cancer tissues was higher than that in pericarcinoma tissues." (PMID 31882379, 2021).
cancer (continued). "MMP-2 (gelatinase-A), and MMP-9 (gelatinase-B) are involved in proteolytic digestion of the extracellular matrix (ECM) for cancer invasion and metastasis." (PMID 34830320, 2021). "The up-regulation of MMP9 (matrix metallopeptidase 9 (gelatinase B) is in line with the reported higher expression in the serum of patients with lung and prostate cancer." (PMID 34209090, 2021). "Recent discoveries have suggested that NE and MMP9 blockades in vitro prevent cancer from re-entering cell cycle and block LPS-mediated cancer progression in vivo." (PMID 34503307, 2021). "Sponging the miR-140-3p circSMARCC1 prevents the inhibition of metalloproteinases MMP-2 and MMP-9, enhancing cancer cell metastasis activity." (PMID 34298612, 2021). "In this connection, we have recently demonstrated that the TNF-α induced fusion of human M13SV1-Cre breast epithelial cells with human MDA-MB-435-pFDR1 cancer cells was attributed to matrix metalloproteinase 9 (MMP9) expression." (PMID 34207991, 2021). "Both MMP2 and MMP9 are highly expressed in cancer cells, and they participate in cancer invasion, angiogenesis, and metastasis." (PMID 33923236, 2021). "These processes involve the role of MMP-9 and MMP-2 by altering the ECM components, which causes the cancer cells to invade the neighboring cells." (PMID 34181339, 2021). "Snail and Twist are the hallmarks oncogenic transcription factors that downregulate the expression of epithelial marker E-cadherin and upregulate EMT markers fibronectin, c-Myc, cyclin D1, MMP2, and MMP9 in various cancers." (PMID 34711805, 2021). "MMP9, one of the matrix metalloproteinases (MMPs) that participates in matrix remodeling of tissues, and in cancer migration, invasion, and tumorigenesis, can be secreted by ICLCs such as TCs through homocellular junctions to interact with surrounding cells." (PMID 34376644, 2021). "Metalloproteinases like MMP-2/MMP-9 have been reported earlier to be regulated by FRA-1 in several cancers including GBM." (PMID 34211498, 2021). "To further assess the significance as well as importance of MMP9 to make a comprehensive understanding, we evaluated the expression pattern of MMP9 in different cancers from GEPIA2 database, such as SARC, GBM, KIRC, LUSC, COAD and BLCA." (PMID 34261456, 2021). "Type I collagenases such as MMP-2 and MMP-9 participate in cancer growth and invasion by degrading extracellular matrix (ECM)." (PMID 34400947, 2021). "To evaluate the potential impact of CM administration, we conducted a pan-cancer survival analysis focusing on the regulation of three genes such as MMP9, Runx2, or Snail." (PMID 34373756, 2021). "MMP2 and MMP9 can degrade type IV collagen and promote the invasion and migration of malignant tumors." (PMID 34497265, 2021). "Through luciferase and western blot assays, by the decreased cell invasion, migration, and cancer metastasis observed, we demonstrated that miR-942-3p repressed MMP9 expression." (PMID 34376644, 2021). "Myeloid-derived suppressor cells (MDSCs) release chemokines including IL-6, VEGF, FGF-2 and MMP-9 to promote cancer progression and bone metastasis." (PMID 34831167, 2021). "In parallel, MMP-9 enzyme is considered to be an important driver of cancer’s malignant progression, invasion and metastasis." (PMID 34344421, 2021). "Overall expression as well as imbalance of MMP9 are associated with a variety of diseases, regulating and inhibiting MMP9 is an essential therapeutic approach to treat various diseases including cancer." (PMID 34261456, 2021). "Changes in EMT markers such as matrix metalloproteinases 2 and 9 (MMP-2 and MMP-9), Vimentin, Snail, and E-Cadherin lead to the displacement of the cancer cell to the systemic environment, which further localized at distant places to form metastatic nodules." (PMID 34535685, 2021). "This suggests that SSP1 and MMP9 are downstream target genes of the HOXB9/TGFβ/Smad2 pathway in the regulation of cancer metastasis." (PMID 34247196, 2021).